SACK1A-AS1 (SACK1A antisense RNA 1)
Synonyms: HCCC11; FAM83A-AS1; HCCC11_v1; HCCC11_v2
Gene: Long non-coding RNA gene on chromosome 8 (123,193,501 to 123,202,743, reverse strand). Ensembl gene ENSG00000204949.
Diseases named in the same sentence as SACK1A-AS1 in open-access papers:
SACK1A-AS1 is named in the same sentence as 2 diseases in open-access papers, as found by Europe PMC text mining. Sharing a sentence is not in itself a finding about the gene and the disease.
SACK1A-AS1 shares sentences with these, for which no sentence is quoted: lung adenocarcinoma (1 paper); non-small cell lung carcinoma (1).